IL10 (interleukin 10)
Diseases named in the same sentence as IL10 in open-access papers (continued):
Sharing a sentence is not in itself a finding about the gene and the disease.
atherosclerosis (continued). "At the same time, Hermansson et al56 showed that immunotherapy with DCs treated with ApoB100 and IL‐10 attenuates atherosclerosis in hypercholesterolemic mice." (PMID 27919929, 2016). "These include in particular Th1-cell lineage which are pro-atherogenic via the secretion typically of IFN-γ and TNF-α, and Th2-cell lineage secreting IL-4, IL-10 and IL-13 whom their role in atherosclerosis remains controversial, including Th1 and Th2 cells." (PMID 26600018, 2015). "The major roles of IL-10 in terms of atherosclerosis include inhibition of macrophage activation, as well as inhibition of matrix metalloproteinase, pro-inflammatory cytokines and cyclooxygenase-2 expression in lipid-loaded and activated macrophage foam cells." (PMID 25948070, 2015). "Low levels of vitamin D increase TNF-α levels and decrease IL-10 levels because TNF-α worsens intimal atherosclerosis and vascular calcification and IL-10 has antiatherogenic properties." (PMID 26618538, 2015). "Both of these are known to be associated with lower cholesterol levels and both of TGFβ1 and IL10 are known to inhibit the development of atherosclerosis." (PMID 26187646, 2015). "This includes our “gold standard” IL10 gene, which has been utilized by at least three groups for inhibiting atherosclerosis." (PMID 26187646, 2015). "Previously, for example, we have shown that STAT3 gene delivery, down-stream of interleukin 10 (IL-10), can substitute for IL-10 gene delivery in the inhibition of atherosclerosis in a mouse model." (PMID 25236373, 2014). "IL-10 has been shown to reduce atherosclerosis and it can be found in atheromatous plaque due to local macrophages production." (PMID 24741576, 2014). "Tregs produce large amounts of TGF-β and IL-10 and play an important role in the process of atherosclerosis by repressing immune function and thus provide a promising target for the modulation of the disease." (PMID 24466164, 2014). "“IL-10 signalling”, “Communication between Innate and Adaptive Immune cells” and “Atherosclerosis Signalling” pathways were also most significant at 1 hour and then diminished in significance over time." (PMID 24842522, 2014). "As expected, atherosclerosis is increased in IL-10−/− mice and IL-10−/−/ApoE−/− double knock-out mice." (PMID 22844641, 2012). "IL-10, which is derived from monocytes and macrophages, is an important anti-inflammatory regulator for the development of advanced atherosclerosis." (PMID 22577254, 2012). "IL-10 is considered an anti-inflammatory cytokine with a potentially protective actions against development of both endothelial dysfunction and atherosclerosis." (PMID 23300769, 2012). "Studies with Il10−/−Apoe−/− mice confirmed the atheroprotective properties of IL-10 in early stage atherosclerosis and showed that IL-10 promotes the stability of advanced plaques." (PMID 22577254, 2012). "Consistent with a protective role of IL-10 in atherosclerosis, overexpression of IL-10 decreases formation of early fatty streak, prevents exaggerated advanced atherosclerosis development, and modulates cellular and collagen plaque composition in mice." (PMID 22556042, 2012). "In mice, leukocyte-derived IL-10 prevents the development of advanced atherosclerosis and plays a critical role in the modulation of the cellular and collagen plaque composition." (PMID 23185530, 2012). "In contrast, TNF production was reduced to a lesser extent than IL-10, unaffected or even slightly increased, when stimulated with LPS from P. gingivalis, one of infectious agent of atherosclerosis." (PMID 22556042, 2012). "This study was to evaluate the feasibility of using in vivo MR imaging (MRI) to monitor BMC-mediated interleukin-10 (IL-10) gene therapy of atherosclerosis." (PMID 21915349, 2011). "The anti-inflammatory and anti-atherogenic properties of IL-10 have been demonstrated using several models of atherosclerosis in mice." (PMID 21673935, 2011).
atherosclerosis (continued). "In conclusion, this study has confirmed the possibility of using in vivo MRI to track IL-10/Feridex-BMCs migrated to atherosclerotic lesions, where IL-10 genes function to prevent or slow the progression of atherosclerosis." (PMID 21915349, 2011). "This study has confirmed the possibility of using MRI to track, in vivo, IL-10/Feridex-BMCs recruited to atherosclerotic lesions, where IL-10 genes function to prevent the progression of atherosclerosis." (PMID 21915349, 2011). "Intranasal immunization with apoB-CTB induced IL-10 producing Tr1 that inhibited effector responses to apoB-100 and reduced atherosclerosis." (PMID 22069660, 2010). "Another approach using AAV vectors has been to try to counteract the development of atherosclerosis by gene transfer of interleukin-10 (IL10), an anti-inflammatory cytokine." (PMID 21144047, 2010). "Conversely, in B cells, patients with atherosclerosis and elevated cortisol levels exhibit a reduced percentage of IL-10–producing B cells, suggesting that cortisol may inhibit IL-10 production in this cell type." (PMID 40627441, 2025). "Tregs suppress immune responses in atherosclerosis by secreting anti-inflammatory cytokines such as interleukin-10 (IL-10) and TGF-β, and they can also maintain the integrity of the fibrous cap by inhibiting Th1 cell activity, reducing macrophage activation, and preventing collagen degradation." (PMID 40821806, 2025). "At the same time, IL-6 triggers the release of IL-1RA and IL-10, which have anti-inflammatory properties and may protect against atherosclerosis." (PMID 39957063, 2025). "Further studies have corroborated these findings, indicating that elevated levels of TNF-γ and IFN-γ, alongside reduced levels of IL-10 in individuals with Chagas disease, may hasten the progression of atherosclerosis and subsequently lead to ischemic stroke." (PMID 39217407, 2024). "Furthermore, butyrate treatment of Ea.hy926 cells has been found to reduce ox-LDL uptake, CD36, VCAM-1, TNF-α, and interleukin-1β/6 production while increasing IL-10 production, suggesting its potential as a treatment for atherosclerosis." (PMID 39275259, 2024). "And IL-10 also can prevent CVDs such as atherosclerosis and hypertension." (PMID 39195548, 2024). "In atherosclerosis, Treg cells stimulate macrophage production of IL‐10 by secreting interleukin‐13 (IL‐13), and autocrine‐paracrine signaling of IL‐10 induces vav guanine nucleotide exchange factor 1 in macrophages, which activates Rac1 and facilitates macrophage cytokinesis." (PMID 39188510, 2024). "Overall, PTP1B potentially promotes atherosclerosis by enhancing a macrophage pro-inflammatory phenotype, regulating oxidative stress, altering the levels of circulating lipoproteins in an IL-10-dependent manner and dysregulating cholesterol efflux in macrophages." (PMID 39000313, 2024). "Conversely, atherosclerosis was accelerated in vivo with genetic inactivation of IL-10." (PMID 39062180, 2024). "IL-10, a soluble cytokine produced by macrophages and regulatory T cells, provides a potential alternative to conventional anti-inflammatory treatments for atherosclerosis, although effective delivery of IL-10 that avoids off-target effects remains a significant challenge." (PMID 38505610, 2024). "However, a chronic increase in osteopontin promotes atherosclerosis and decreases anti-inflammatory atheroprotective cytokines, e.g., IL-10." (PMID 39539344, 2024).
atherosclerosis (continued). "When the miR-155 in the macrophages was expressed, the IL-10 mRNA in the exosome could be delivered into macrophages and other cells in the plaque, and later the IL-10 mRNA would translate into protein, which could alleviate the atherosclerosis in the model." (PMID 39296981, 2024). "Notably, IL-10 and TGF-β have been identified as major cytokines associated with atherosclerosis regression." (PMID 38774876, 2024). "They then generated apoE-deficient mice with myeloid-specific inactivation of IL-10 and demonstrated that these mice exhibit a pro-inflammatory state, with significantly increased expression of TNF-ɑ, and CCL2, a chemokine linked to atherosclerosis as well as a trend toward increased IL-1β." (PMID 39062180, 2024). "IL-10, in turn, enhances efferocytosis in advanced atherosclerosis via the IL-10/Vav1/Rac1 pathway." (PMID 39660125, 2024). "IL-10 is a potent anti-inflammatory cytokine that can control inflammation and induce tissue healing, and its production is reduced in chronic inflammation, such as atherosclerosis and multiple sclerosis." (PMID 39062154, 2024). "IL-10 secreted by Th17 cells may prevent the recruitment of T cells and macrophages and enhance protection against atherosclerosis by promoting the transformation of macrophages from an inflammatory to an anti-inflammatory phenotype." (PMID 38143759, 2023). "Furthermore, nanoparticle-mediated silencing of macrophage ODC1 during atherosclerosis decreases IL-10 expression, lowers efferocytosis, and worsens necrotic core area and fibrous cap thickness." (PMID 36710920, 2023). "Our objective was to determine which BBB characteristics are produced mainly by interleukin (IL)-6, an atherosclerosis promoting cytokine, and whether these actions can be antagonized by IL-10, an anti-inflammatory cytokine." (PMID 36882782, 2023). "Indeed, IL-10 had been used as the systemic inflammation biomarker to assess the anti-inflammatory effect of the exercise in atherosclerosis, myositis, and inflammatory myopathies." (PMID 37403092, 2023). "STAT3 phosphorylation was previously identified as a major inducer of the inflammation-resolving M2 phenotype in macrophages by increasing IL-10 expression and was suggested as a potential mechanism for the protection of ApoE LysMPTP1B(−/−) mice against atherosclerosis." (PMID 37828508, 2023). "Thus, disturbances in CCL1-CCR8 can inhibit the production of IL-10, reduce the number and functions of regulatory T cells, which leads to the development of atherosclerosis." (PMID 37047399, 2023). "A very recent study revealed the role of macrophage derived IL-10 in limiting atherosclerosis." (PMID 36994095, 2023). "Thus hamsters are an ideal model to better understand the influence of IL-10 on lipoprotein metabolism and atherosclerosis." (PMID 36110841, 2022). "SARS-CoV-2 infection stimulates secretions of IL-1β, interferon-γ (IFN-γ), IFN-γ-induced protein 10kDa (IP-10), monocytic chemoattractant protein-1 (MCP-1), interleukin-4 (IL-4), IL-6, and interleukin-10 (IL-10), some of which can trigger a cytokine storm and atherosclerosis in a host." (PMID 36289895, 2022). "The main cytokine secreted by Tregs, IL-10 plays an important role in regulating atherosclerosis." (PMID 36211578, 2022). "However, IL-10 therapy for atherosclerosis and its effect on vascular remodeling remains to be investigated." (PMID 35600479, 2022). "IL-10 significantly affects the inflammatory response in atherosclerosis." (PMID 36211578, 2022). "However, the relationship between IL-10 and atherosclerosis is still under debate due to contradictory results from clinical and experimental studies." (PMID 36110841, 2022).
atherosclerosis (continued). "We review the mechanisms of CD4+ T subsets, i.e., helper T17 (Th17) cells and regulatory T cells (Tregs), in regulating atherosclerosis, focusing on the role of interleukin (IL)-17, IL-10, and other cytokines in this disease and the factors influencing the effects of these cytokines." (PMID 36211578, 2022). "IL‐10 is a well‐known anti‐inflammatory cytokine, known to modulate lipid metabolism, promote M2 macrophage differentiation, inhibition of matrix metallo‐proteases and provides protection against atherosclerosis." (PMID 35094491, 2022). "Human IL-10 gene transfer decreased atherosclerosis and atherosclerotic plaque instability." (PMID 35303193, 2022). "Correlations among constitutive expression of IRAK1 in the peripheral blood mononuclear cells isolated from patients with atherosclerosis, elevated levels of the plasma IL-10, and the stimulation effect of IRAK1 on IL-1, imply direct involvement of IRAK1 in atherosclerotic development." (PMID 35345264, 2022). "Activation of IRAK1 enhances production of IL-10 and patients with atherosclerosis often have an elevated level of IL-10, implying that the IRAK1-mediated innate immune response may play an important role in the development of atherosclerosis." (PMID 35345264, 2022). "IL-10 is a pleiotropic cytokine that has been proposed as a hazard modifier for atherosclerosis." (PMID 35607519, 2022). "The molecular mechanisms by which IL-10 may modulate lipid metabolism to influence the development of atherosclerosis are largely unknown." (PMID 36110841, 2022). "Low levels of Il-10 are, therefore, associated with atherosclerosis and are considered to be one of the non-classical proatherogenic factors." (PMID 34771080, 2021). "Aortic root intimal area was inversely correlated with plasma IL-10 levels, but not total cholesterol concentrations, suggesting inflammation but not plasma cholesterol was responsible for increased atherosclerosis in bone marrow SLC37A2-deficient mice." (PMID 34957260, 2021). "Besides their role as antigen-presenting and Ig-secreting cells, B cells secrete cytokines, which have the potential to either promote (TNFα, INFγ, IL-12) or ameliorate (IL-2, IL-4, IL-10, TGFβ) the development of atherosclerosis." (PMID 33572939, 2021). "Therapeutic delivery of IL-10 has been shown to suppress atherosclerosis 16-19." (PMID 34815799, 2021). "Exosome-based delivery of the engineered Il-10 mRNA could alleviate the atherosclerosis in ApoE-/- mice while had minimal side-effects." (PMID 34815799, 2021). "However, the immunoinflammatory response in atherosclerosis is modulated by the regulatory pathways in which the two anti-inflammatory cytokines, interleukin 10 (IL-10) and transforming growth factor β (TGF-β), play a critical role." (PMID 34901005, 2021). "Exosome-based delivery of the engineered Il-10 mRNA could alleviate the atherosclerosis in ApoE-/- mice while had minimal side-effects, allowing long and systemic application in the future." (PMID 34815799, 2021). "IL-10+ B cells have also been recovered from tertiary lymphoid organs in arteries of atherosclerotic mice, suggesting that in atherosclerosis (like in neuroinflammation), Bregs may also suppress inflammation in situ." (PMID 33995344, 2021). "Consistent with the robust Il-10 induction in the plaque, exosome-based delivery of the engineered Il-10 could alleviate the atherosclerosis in ApoE-/- mice." (PMID 34815799, 2021).
atherosclerosis (continued). "IL-10 has the functions of anti-inflammatory for the atherosclerosis disease." (PMID 34568579, 2021). "In the spleen of atherosclerosis-prone mice, increased IL-10+ B cells have been detected." (PMID 33995344, 2021). "To date, the contribution to atherosclerosis has been addressed for IL-10, IL-19, and IL-22." (PMID 33562334, 2021). "Interestingly, cortisol suppressed IL-10 expression via miR-98 in cultured B lymphocytes suggesting therapeutic potential of targeting miR-98 in atherosclerosis." (PMID 33988232, 2021). "Regarding the suppressive actions of Tregs in atherosclerosis, IL-10 and TGF-β production might be involved in this process." (PMID 34945203, 2021). "Consistent with the robust Il-10 mRNA induction in the plaque, exosome-based delivery of the engineered Il-10 mRNA could alleviate the atherosclerosis in ApoE-/- mice." (PMID 34815799, 2021). "Generally, our study established a potent platform for tailored inflammation control via exosome-based systemic and repeated delivery of engineered Il-10 mRNA, which could be a promising strategy for atherosclerosis treatment." (PMID 34815799, 2021). "On the other hand treatment with captopril promoted the production of anti-inflammatory IL-10 in various models of diseases induced in rats and mice as radiation-induced lung inflammation, biliary hepatitis, atherosclerosis, and hypertension as well as in normal mouse splenocytes." (PMID 34768805, 2021). "Then, we delivered the engineered Il-10 mRNA via exosomes for the treatment of atherosclerosis." (PMID 34815799, 2021). "Our study established a potent platform for tailored inflammation control via exosome-based systemic and repeated delivery of engineered Il-10 mRNA, which could be a promising strategy for atherosclerosis treatment." (PMID 34815799, 2021). "Recently, IL-10 has also been examined for its therapeutic role in atherosclerosis." (PMID 32117582, 2020). "Interleukin-10 (IL-10) was an antiatherogenic inflammatory cytokine that played the protective role in coronary atherosclerosis, and IL-10 deletion accelerated the progression of atherosclerosis." (PMID 33029103, 2020). "Antiatherogenic inflammatory cytokine IL-10 therapy may be a novel approach to treat atherosclerosis for the future." (PMID 33029103, 2020). "Moreover, the endothelial hypoxia-inducible factor-1α promoted atherosclerosis and monocyte recruitment by upregulating miR-19a7, while TNF-α or IFN-γ or IL-4 suppressed IL-10 in B cells (from patients with atherosclerosis) via upregulating miR-19a expression." (PMID 32308549, 2020). "IL-6 is an inflammatory cytokine that plays a central role in propagating the downstream inflammatory response that sustains atherosclerosis progression, whereas IL-10 is a prototypic anti-inflammatory cytokine released by activated macrophages that delays the growth of vascular lesions." (PMID 32717800, 2020). "Researchers have concluded that in atherosclerosis, interleukins such as IL-4, IL-13, and IL-10 activate specific transcription factors (e.g., STAT3 and STAT6, IFN regulatory factor 3, peroxisome proliferator-activated receptor-γ [PPARγ]) in macrophages to encourage inflammation resolution." (PMID 32346605, 2020). "Thus, we inferred that NONMMUT002434 promote atherosclerosis by inhibiting IL10 and BIRC5, thus promoting inflammation and cell apoptosis." (PMID 30850398, 2019).